KRAS (KRas proto-oncogene, GTPase)
Diseases named in the same sentence as KRAS in open-access papers (continued):
Sharing a sentence is not in itself a finding about the gene and the disease.
adenocarcinoma (continued). "KRAS mutations (MT) are more common in adenocarcinoma than in other NSCLC histologies." (PMID 26471290, 2015). "KRAS mutational analysis was performed for 720 samples and 26.5% (191 out of 720) of the cases were mutated, mainly adenocarcinomas (29.9%, 164 out of 549 adenocarcinomas)." (PMID 26208325, 2015). "BRAF mutation is more specific to serrated adenocarcinomas than KRAS." (PMID 25945086, 2015). "The mutated KRAS subgroup of patients had, as expected, a higher percentage of adenocarcinoma histology (85.0% compared to 65.8% for mutated and wild-type respectively) and a lower prevalence of never smoker patients (6.7% compared to 22.5% for mutated and wild-type respectively)." (PMID 26416458, 2015). "This suggests that KRAS mutated AAH may not progress to adenocarcinoma in the same way proposed for EGFR mutated AAH, and that KRAS mutations occur in adenocarcinoma de novo via an alternative pathogenesis." (PMID 24742923, 2014). "It enabled indeed a correct identification of known KRas oncogenic mutations in adenocarcinomas." (PMID 25184754, 2014). "Secondly, EGFR-mutated adenocarcinomas were weakly associated with higher fractions of total LOH compared with KRAS-mutated and EGFRwt/KRASwt tumors both overall and in stage I disease (p=0.05, ANOVA), but not in tumors of higher stages (≥II), or tumors stratified by gender." (PMID 24205279, 2013). "The KRAS c12G→A transition was the predominant type of mutation in serrated adenocarcinomas." (PMID 21457162, 2011). "As KRAS mutations were mainly observed in patients with adenocarcinoma histology, this could have been confounding the favourable prognostic effect we observe for KRAS mutations." (PMID 19050706, 2009). "However, this prognostic effect of KRAS mutations is mainly observed in adenocarcinomas of the lung." (PMID 19050706, 2009). "In addition, PFS may be shorter in patients with KRAS mutated adenocarcinoma histology (4.3 vs. 6.7 months; p = 0.051)." (PMID 35070984, 2021). "Interestingly, moderately and poorly differentiated adenocarcinomas harbored KRAS mutations (18% and 17% respectively) more frequently than well-differentiated adenocarcinomas, suggesting potential de novo carcinogenesis as a result of KRAS mutations and additional genomic events." (PMID 29690599, 2018). "However, more plausible explanations include de novo developments from normal lung epithelium to KRAS- or BRAF-mutated invasive adenocarcinomas as a result of KRAS or BRAF mutations and additional genomic changes, including genomic instability caused by defective DNA repair or smoking." (PMID 29690599, 2018). "In addition, KRAS gene exon 2 G12C presented mutation in the OSP-associated adenocarcinoma." (PMID 29879069, 2018). "Interestingly, non-synonymous somatic missense mutations of KRAS were detected in four out of the six (66.67%) early-stage adenocarcinoma analysed with a frequency even higher than that described in early and advanced-stage adenocarcinoma of high-risk individuals (32% and 35% respectively)." (PMID 28194229, 2017).
adenocarcinoma (continued). "Adenocarcinoma was prevalent in 706 (66%) patients, with 218 (20%) exhibiting EGFR mutations and 304 (28%) with KRAS mutations." (PMID 41245885, 2025). "Because KRAS is generally only present in adenocarcinomas, this relation is likely driven by histology." (PMID 40029549, 2025). "In KRAS-mutant adenocarcinoma subgroup, OS was similar between Q1 and Q4 groups (HR 1.14, 95% CI 0.98–1.32, p = 0.10)." (PMID 40940992, 2025). "Adenocarcinomas frequently harbor driver mutations such as EGFR, KRAS, and ALK rearrangements, which modulate immune landscapes." (PMID 40342732, 2025). "In KRAS-mutant adenocarcinoma, the median OS was 20.9 months in Q1 compared to 20.2 months in Q4 (HR 0.99, 95% CI: 0.91–1.08, p = 0.75)." (PMID 40940992, 2025). "A study of 102 cases of LCLC revealed that adenocarcinoma-associated mutations (EGFR, KRAS, BRAF, and ALK) occurred exclusively in the null immunophenotype or adenocarcinoma-differentiated LCLC." (PMID 40898486, 2025). "Limited evidence suggests possible co-expression of ERβ with ALK-EML4 fusions (single case report), while KRAS-mutant adenocarcinomas frequently exhibit ERβ expression - though these observations require larger clinical validation." (PMID 40739091, 2025). "The overall cohort included 78.9% patients with NSCLC adenocarcinoma histology, 31.5% with PD-L1 score of 1+, 7% with +EGFR mutations, and 18.3% with +KRAS mutations." (PMID 40636413, 2025). "The most common driver mutations are EGFR (present in 45% of Asian and 20% of Caucasian adenocarcinoma patients) and KRAS (found in 25% of adenocarcinomas)." (PMID 39852181, 2025). "Adenocarcinoma is often associated with genetic mutations such as EGFR (epidermal growth factor receptor), ALK (anaplastic lymphoma kinase), and KRAS (Kirsten rat sarcoma viral oncogene homolog), making it a target for precision therapies." (PMID 40728967, 2025). "In the current study, we used the CRISPR/Cas9 system to knock down PD-L1 and KRAS in adenocarcinoma lung cells (A549 and H1975)." (PMID 39201772, 2024). "Significant differences can be found in the mutation rate of EGFR (60.9% vs 11.9%), KRAS (12.2% vs 25.0%), STK11 (1.5% vs 11.9%), FGFR3 (2.4% vs 0.0%) and ERBB4 (1.2% vs 6.1%) between adenocarcinoma in our cohort and TCGA-LUAD data (all p < 0.001)." (PMID 38496837, 2024). "The frequency of KRAS alterations in pancreatic (92.2%) and colorectal (45.5%) adenocarcinomas was significantly higher than that in the stomach (20.0%) and biliary tract (21.2%) adenocarcinomas (p < 0.01)." (PMID 38672586, 2024). "Mechanisms of acquired resistance to KRAS G12C inhibitors include MAPK pathway mutations, transformation from adenocarcinoma to squamous histology, alternative KRAS alterations, and a high degree of KRAS G12C amplification." (PMID 38672633, 2024). "For example, KRAS and EGFR mutations frequently occur in adenocarcinoma, while SCC has a much lower prevalence of these mutations." (PMID 38994972, 2024). "In NSCLC, in particular in adenocarcinoma, mutations are common in epidermal growth factor receptor (EGFR) and Kirsten rat sarcoma viral oncogene homolog (KRAS)." (PMID 38926762, 2024). "Although these cells are classified as Adenocarcinoma, their outgrowth patterns vary depending on their oncogene expressions (KRAS or EGFR)." (PMID 39180048, 2024). "Somatic STK11 disruption is common in KRAS-driven LUADs (~10–15%), but rare in other KRAS-driven adenocarcinomas (pancreatic ~1.5%, colorectal ~1.2%)." (PMID 37968341, 2024). "In these patients, KRAS mutant adenocarcinoma of mucinous character frequently appears later, indicating to the oncogenic nature of the mutation." (PMID 38953007, 2024). "In patients with adenocarcinoma, the EGFR and KRAS mutation rates were 52.79% and 10.12%, respectively." (PMID 39364008, 2024).
adenocarcinoma (continued). "These cells, both categorized as adenocarcinomas, had distinct genetic profiles: one harboring the KRAS oncogene (HCC 4087) and the other the EGFR oncogene (HCC 4190)." (PMID 39180048, 2024). "KRAS, BRAF, STK11/KEAP1, MUTYH/RET, and RBM10/MET-associated modules showed the opposite trend, having significantly higher frequencies of adenocarcinoma cases as genomic alterations increased (P ≤ 0.02)." (PMID 39664186, 2024). "Colorectal (40.6%) and pancreatic (45.3%) adenocarcinomas were the most common digestive adenocarcinomas with KRAS alterations." (PMID 38672586, 2024). "In non-adenocarcinoma cases, one EGFR Ex.19 deletion, one KRAS G12C mutation, two KRAS other mutations, and one MET Ex.14 skipping were detected with the ODxTT; meanwhile, no driver alterations were detected with the AmoyDx-multi test." (PMID 38730622, 2024). "It was of interest to compare the effect of PD-L1 and KRAS silencing in these adenocarcinoma cell lines." (PMID 39201772, 2024). "KRAS is the most frequently mutated oncogene in NSCLC, especially found in adenocarcinomas in 20–30% of cases." (PMID 38785486, 2024). "For this study, we chose NCI-H441 as a model adenocarcinoma cell line expressing 3–4 genomic copies of G12V to wild-type KRAS per cell." (PMID 37105964, 2023). "Another common gene detected in adenocarcinoma among smokers is the Kirsten rat sarcoma viral oncogene homolog gene (KRAS)." (PMID 36661704, 2023). "In both cell lines, a KRAS missense mutation is present (H358: KRAS-G12C, A549: KRAS-G12S), as reported in the supplier (ATCC) product sheet, and they are histologically characterized as adenocarcinoma." (PMID 37173939, 2023). "It was recently reported that KRAS gene abnormalities in ASC of the pancreas resemble those in adenocarcinoma." (PMID 37773552, 2023). "In contrast to better-known driver alterations in adenocarcinoma, such as EGFR, KRAS, and ALK, passenger mutations seem to contribute to the high somatic mutation rate in LUSC." (PMID 36873930, 2023). "It is possible that KRAS gene abnormalities in SCC of the pancreas are also similar to those in adenocarcinoma." (PMID 37773552, 2023). "For example, in colorectal SRCC, loss of E‐cadherin protein expression and a higher frequency of KRAS were noticed compared to conventional adenocarcinoma in the same study." (PMID 36779496, 2023). "Matched trial therapies were available for 20% (3/15) of patients with adenocarcinoma (NOS), 13% (2/15) to AKT1 inhibitors (NCT01226316, NCT02338622) and 7% (1/15) to RAF/MEK inhibitors, based on a KRAS mutation through NCT02407509." (PMID 35267442, 2022). "PACER expression was also increased, but to a lesser degree, in H1975 cells (t(2.14) = 8.33, p = 0.012) and the mutant KRAS adenocarcinoma cell line H1373 (t(2.39) = 6.332, p = 0.015)." (PMID 35136486, 2022). "Limited data were available for PD-L1 expression in SCLC, LCNEC, KRAS mutant adenocarcinoma, and other less common forms of NSCLC, making evaluation difficult." (PMID 36136862, 2022).
adenocarcinoma (continued). "The oncogenic activation of endogenous KRAS caused mostly EMT-like, spindle cell tumors and fewer poorly differentiated adenocarcinomas (top and middle)." (PMID 34145248, 2021). "To test the clinical significance of FoxM1 activation, we analyzed a cohort of KRAS mutant adenocarcinoma samples collected from patients undergoing surgical resection." (PMID 34573384, 2021). "Response to Selumetinib was initially assessed on six commercially available KRAS mutant adenocarcinoma cell lines, of which four (H23, H358, H1734 and SK-LU-1) retained a copy of the WT allele." (PMID 34573384, 2021). "KRAS and EGFR mutations, as well as ALK rearrangements are the main oncogenic drivers in adenocarcinomas." (PMID 34781949, 2021). "Our findings therefore hold promise for the development of a targeted therapy for KRAS-mutant adenocarcinomas." (PMID 33854168, 2021). "Histologically, KRAS/SMAD4 KO tumors were moderately differentiated adenocarcinomas exhibiting glandular growth patterns." (PMID 33674596, 2021). "F+D had positive effects on synergy against the growth of murine KRAS mutant adenocarcinoma cells, as well as the production of a strong immune cell infiltrate in syngeneic hosts implanted with tumors." (PMID 35008514, 2021). "Among adenocarcinomas, EGFR and KRAS mutations were present in 55.6% (15/27) and 22.2% (6/27) of tissue samples, respectively." (PMID 32196518, 2020). "Among patients diagnosed with adenocarcinoma, mutational analysis was performed in 13 cases, one patient showed EGFR mutation, four patients KRAS mutation, while PD‐L1 expression was confirmed in three samples." (PMID 32401433, 2020). "For instance, adenocarcinoma is generally induced in part to alterations in KRAS, ALK, ROS proto-oncogene 1 (ROS1), Ret proto-oncogene (RET), neurotrophic receptor kinase 1 and neuregulin." (PMID 32316322, 2020). "CNA gain of KRAS was more common in the mucinous MSS cohort compared to the adenocarcinoma NOS MSS cohort (46.4% vs. 7.4% p = 0.002)." (PMID 32984045, 2020). "Compound 18 was evaluated for its antiproliferative activity against A549, adenocarcinoma human alveolar basal epithelial cell line, which overexpresses HER2 and possesses wild type EGFR and KRAS mutation." (PMID 32922539, 2020). "The KM mouse model faithfully recapitulates key molecular events in human adenocarcinoma of the lung and is a useful tool for mechanistic interrogation of KRAS-driven LuAd progression." (PMID 31032816, 2019). "Despite of the small sample size of this cohort (n = 40), the mutation profiles identified support previous findings that the majority of adenocarcinomas associated mutations occur in EGFR exon 19 and 21 and that KRAS and EGFR mutations are mutually exclusive." (PMID 31841547, 2019).
adenocarcinoma (continued). "For example the analysis of KRAS mutations, which is present in 15–25% of the patients, is suspected to be a prognostic biomarker of worse treatment outcome in NSCLC adenocarcinoma." (PMID 31860648, 2019). "To eliminate the impact of SSN on DESCT quantitative parameters, and since the KRAS mutation adenocarcinoma are all SN as well, we deleted imaging data of SSN and then compared the difference between the two groups (KRAS n = 12 to EGFR n = 44)." (PMID 31783917, 2019). "Nodule type differed significantly between the KRAS and EGFR groups (P = 0.035), and all KRAS mutation adenocarcinomas were solid nodules." (PMID 31783917, 2019). "In conclusion, the SN proportion was higher with KRAS than EGFR mutations and all KRAS mutation adenocarcinomas were SN tumors." (PMID 31783917, 2019). "To study the impact of HCI‐2509 on KRAS‐mutated adenocarcinoma in vivo, we used C57BL/6N(KRAS G12V) mice, in which the constitutively active KRAS form is induced via adenoviral Cre application." (PMID 30220105, 2018). "Compared to conventional adenocarcinoma, CNEC frequently exhibited BRAF mutations (59% vs. 5%) and less frequently displayed KRAS mutations (17% vs. 43%); the large majority (93%) of CNECs showed proficient mismatch repair." (PMID 29652830, 2018). "The study of KRAS-induced mouse adenocarcinomas allowed to define the various Ras-induced pathways acting downstream this mediator, that, can be potentially targeted in view of novel therapeutic strategies." (PMID 30060526, 2018). "Nussinov is currently focused on the Ras protein and its interactions with effectors, with a particular interest in KRAS-driven adenocarcinomas." (PMID 29771916, 2018). "In human adenocarcinomas the frequency of EGFR mutations is estimated between 15 and 45%, whereas KRAS mutation was detected in 20% of the cases depending on the geographical region." (PMID 29415661, 2018). "The efficacy of first line pemetrexed-based chemotherapy was investigated in patients with HER2-mutant and those with EGFR-mutant, ALK/ROS1-rearranged and KRAS-mutant advanced adenocarcinomas." (PMID 29587667, 2018). "In terms of smoking status, KRAS-mutated AAH and adenocarcinoma were more frequently observed in smokers." (PMID 29690599, 2018). "The mutation rate of KRAS was significantly different in different histological types, NRAS and BRAF mutations were only detected in adenocarcinomas." (PMID 30416987, 2018). "Driver genetic mutations, including EGFR, KRAS, and BRAF, are thought to be associated with the initiation and progression of adenocarcinoma as described in this review." (PMID 29690599, 2018). "The suspected primary tumor, a well-differentiated adenocarcinoma of the transverse colon with wild-type KRAS was found by colonoscopy, and treatment with 5-fluorouracil, leucovorin, and oxaliplatin (modified FOLFOX6) plus panitumumab was initiated." (PMID 28228152, 2017). "Among HER2-amplified adenocarcinomas, 24 (52.2%) and 3 (6.5%) had EGFR and KRAS mutations, respectively, while 1 (2.2%) showed ALK rearrangement." (PMID 28146588, 2017). "Approximately 25%–30% of NSCLC have Kirsten rat sarcoma viral oncogene homolog (KRAS) mutations, mostly adenocarcinomas." (PMID 28430151, 2017). "Presence of multiple KRAS mutations (G12V and G12D) was observed in 5 patients using dPCR, all of whom had FNA cytological diagnosis of “adenocarcinoma” and surgical pathologic diagnosis of PDAC." (PMID 28125707, 2017). "In a high-throughput screening program in NSCLC, miR-155 was upregulated only in EGFR/KRAS negative group, miR-25 was upregulated only in EGFR positive group and miR-495 was upregulated only in KRAS positive adenocarcinomas." (PMID 28771186, 2017). "For adenocarcinoma, the dominant histological subtype of lung cancer, increased understanding of molecular pathogenesis such as EGFR mutation, KRAS mutation and ALK fusion leads to the success of targeted therapy." (PMID 28852126, 2017).